CD46 (CD46 molecule)
Diseases named in the same sentence as CD46 in open-access papers (continued):
Sharing a sentence is not in itself a finding about the gene and the disease.
infection (continued). "In spite of increasing virus attachment in heterologous cell lines, overexpression of bovine CD46 is not sufficient to turn cells susceptible to infection." (PMID 34204224, 2021). "HAdV-D49 infection was reduced significantly in all three cell lines when CD46 was blocked." (PMID 34452348, 2021). "LOAd703 is a serotype chimera and uses the serotype 35 fiber for infection via CD46." (PMID 33666760, 2021). "(in vivo) MV infection in transgenic mice expressing human CD46 in the CNS (NSE-CD46)." (PMID 34408631, 2021). "Our results indicate that bovine CD46 is an apical protein and mediates apical infection by BVDV." (PMID 33300445, 2021). "This might indicate a lack or an incompatibility of yet unknown factors in porcine cells that allow for the highly efficient, CD46-independent infection of bovine cells in the presence of the G479R exchange." (PMID 34959575, 2021). "Finally, we investigated CD46 interaction, as it has previously been described as having a potential involvement in HAdV-D49 infection." (PMID 34452348, 2021). "Thus, at a low expression level of CD46, which is typical of normal cells, infection occurs, but intercellular fusion is negligible." (PMID 33291506, 2020). "Thus, the observations made with the Morbillivirus MeV allowed for the identification of the complement regulatory factor CD46 as a pathogen sensor endowed with the capacity to activate autophagy in cells undergoing infection." (PMID 32274388, 2020). "Via its Tfp, Ngo quickly recruits CD46-cyt1 to the site of infection." (PMID 30753248, 2019). "We found 55 InDels related to the CD46 gene in WS cattle, suggesting that WS cattle may have well antiviral infection characteristics." (PMID 31443466, 2019). "At 25 min after infection, fluorescent spots could also be identified in CD46 positive vesicles inside the cell." (PMID 30979966, 2019). "Importantly, this was confirmed by the observation that anti-CD46 mAbs were unable to limit infection by TB40/E wt and AD169BADrUL131 in fibroblasts." (PMID 31221976, 2019). "Interestingly, CMV also enters endothelial cells by the endocytic pathway and thus CD46 probably plays a role in infection of endothelial cells." (PMID 31221976, 2019). "Thus, we propose that CD46 functions as an entry factor that participates in the infection steps such as viral binding, endocytosis, and/or fusion." (PMID 31221976, 2019). "As Ngo induces CD46-cyt1 clustering at the site of infection, we tested the hypothesis that the autophagic response in Ngo-infected cells is mediated by CD46-cyt1." (PMID 30753248, 2019). "Furthermore, HHV-6B strain PL, shown to require CD46-Cyt1 for infection, induced the expression of HERV-K18 mRNA in PBMCs without requirement for viral transcription and replication." (PMID 30574140, 2018). "It was shown that SKOV3 cells are CAR-negative and CD46-postive, and Huh7 cells have higher CAR and CD46 expression than A549 and Hela cells, supporting the hypothesis that CD46 plays a role in HAdV17 infection." (PMID 30194327, 2018). "Furthermore the CD46 competitor efficiently blocked HAdV17GFP infection in EA.hy926 cells, indicating the CD46 plays a prominent role for HAdV17GFP infection in endothelial cells." (PMID 30194327, 2018). "Finally infection of CD46-expressing murine cells with a panel of recombinant EnAd expressing each of the MAV-1 open reading frames also did not enhance MLP-driven GFP expression, though replication-independent GFP expression was improved in some cases." (PMID 29898782, 2018). "In addition, the infection of human epithelial cells by Neisseria, using CD46 SCR3 and STP domain as a receptor, leads to the Cyt2 tyrosine phosphorylation." (PMID 30574140, 2018). "Furthermore, the infection of astrocytes with HHV-6A also leads to downregulation of the receptor CD46 that was used for entering the cell." (PMID 29093709, 2017).
infection (continued). "Consequently, a study in particular with AdV-37, also looked at the utilization of various CD46 isoforms for infection by this serotype." (PMID 28670306, 2017). "We found that Ad43 can use two alternative receptors—CD46 and integrins—for infection." (PMID 27462785, 2016). "The incomplete inhibition of Ad43 infection by the CD46-binding Ad35 fiber and its knob suggested that molecules other than CD46 may function as alternative receptors for Ad43." (PMID 27462785, 2016). "CHO or Vero cells expressing SLAMF1 became susceptible to infections with wtMeV and used this receptor without the need to adapt and use CD46." (PMID 27657109, 2016). "In the CD46+ mouse model, NSPCs are spared from MV-infection." (PMID 27178303, 2016). "Defining the anti-viral cytokine profile in CD46+ and CD46+/IFNγ-KO pups may provide insight into the milieu that is required to maintain the NSPC pool during infection." (PMID 27178303, 2016). "However, protein ratios for STAT1α-P/STAT1α showed that only CD46+ mice increased regulation of phosphorylation during infection." (PMID 27178303, 2016). "To determine whether CD46 plays a role in MPM cell infection, we exposed eight MPM cell lines to MV-ch in the presence of anti-CD46 mAb or isotype control mAb." (PMID 26539644, 2015). "CD46 can play a primary function in the host’s response to pathogens by regulating complement activation, and can also play an important role in CD46-dependent autophagy, which is induced as an innate immune mechanism and is a critical step in the early control of infection." (PMID 25070150, 2014). "Nonetheless, CD46 membrane complement regulatory protein expression still remains the key determinant for cancer cell sensitivity (i) to primary infection by MV and subsequently (ii) to the efficient transmission of new viruses to neighboring cells by formation of multinucleated syncytia." (PMID 23586034, 2013). "Moreover, we showed that cell lines exhibiting high CD46 expression also displayed high infection rates by oncolytic MV." (PMID 23586034, 2013). "They showed that (i) an anti-CD46 antibody inhibited HHV-6B (strain Z29) infection and HHV-6B-mediated cell fusion in PBMCs and (ii) the expression of CD46 in NIH3T3 cells (mouse fibroblasts) and EL4 cells (murine T lymphoblasts) caused HHV-6B- (strain-PL1-) mediated fusion and entry, respectively." (PMID 23133452, 2012). "CD46/IFNAR mice and cynomolgus macaques were chosen for pre-clinical evaluation of MV1-F4, as both species are susceptible to infection with MV vaccine strains and further macaques are susceptible to infection with wild-type MV." (PMID 23226275, 2012). "In support of the notion that CD46 might associate with rafts, a recent study showed that CD46 was recruited to detergent-resistant membranes (DRM) after infection with Human Herpes Virus 6 (HHV6)." (PMID 21490803, 2011). "Besides mediating internalization to enable infection, binding to CD46 can directly alter immune function." (PMID 21490803, 2011). "Our study also revealed a new CD46-independent infection pathway of Ad35." (PMID 18974862, 2008). "Thus, together with the findings of our studies, it appears that Ad16, 21, 35 and 50 nearly exclusively use CD46, Ad11p uses both CD46 and receptor X, while Ad3, 7 and 14 only utilize receptor X as attachment receptors for cellular infection." (PMID 18974862, 2008). "Therefore, increased affinity for HS may sequester the virus away from CD46 or other yet undiscovered entry receptors and thus prevent infection." (PMID 40431646, 2025). "Notably, BVDV is known to acquire HS-adaptive mutations in vitro to overcome infection restriction in MDBK cells lacking CD46." (PMID 40431646, 2025). "Interestingly, astrocytes’ infection by cytomegalovirus upregulates CD46 surface expression." (PMID 36032156, 2022).
infection (continued). "Interestingly, for BVDV-1 strain NADL and BVDV-2 strain CS8644, trans-complementation with CD46-CTS enabled a more efficient infection than CD46-CTL, with approx. three-fold (NADL) and six-fold (CS8644; ***p < 0.001) increased titres in comparison to MDBK WT cells." (PMID 34839792, 2022). "Conceivably, there could be other mechanisms of direct interaction between the cell and capsid surface, such as the hexon-CD46 interaction, recently suggested for HAdV-D56, although it is unclear whether this putative interaction would be sufficient for a productive infection in vivo." (PMID 34851659, 2021). "Therefore, human CD46 promotes entry and infection by Stealth-A09 in relevant cell lines." (PMID 33534834, 2021). "Also, CD46 is not sufficient to render cell lines derived from non-cloven-hoofed animals or humans susceptible to infection with BVDV." (PMID 31963539, 2020). "Similarly, the proportions of cellular compartments—lamellipodium, lamella, and cell body—with associated virus particles were not affected by CD46’s ability to bind E2 when comparing different time points after infection." (PMID 31963539, 2020). "However, the blocking CD46 antibody attenuated, nearly-completely, infection by MV-GFP." (PMID 28968974, 2017). "Moreover, the investigations also revealed that expression of CD46 on the non-permissive cells renders them susceptible to viral attachment and infection." (PMID 28670306, 2017). "However, future studies will examine the cytokine expression profile over the course of infection in CD46+ pups, which may provide an explanation as to the reduction in STAT1 and STAT2 signaling by 10 dpi." (PMID 27178303, 2016). "However, total STAT2 levels increased independently of infection over time in CD46+ explants." (PMID 27178303, 2016). "To identify the primary receptor(s) for Ad43, we first tested whether Ad43 uses CD46 for infection." (PMID 27462785, 2016). "Our results may also suggest reevaluating the role of CD46 in infection." (PMID 26084023, 2015). "CHO cells are not susceptible to infection by MV strains and do not express CD46, SLAM or PVRL4." (PMID 25171206, 2014). "Contrary to most primate CD46 proteins, murine CD46 has a lower percentage of identity with the human protein and its expression is restricted to the testis, which may account for the resistance of mice to infection." (PMID 23847599, 2013). "In addition to its role in regulation complement activation, CD46 is also used by a large number of pathogens, including measles virus and adenovirus, as a receptor to allow these pathogens to attach to the cell surface and initiate an infection." (PMID 20941397, 2010). "Thus, infection of CD46 transgenic mice leads to three different patterns of disease." (PMID 17311106, 2007). "This study provides comprehensive evidence that HAdV-7 utilizes CD46 and DSG2 as synergistic co-receptors to mediate efficient infection, viral replication, and inflammatory pathology." (PMID 41989164, 2026). "This study provides comprehensive evidence that HAdV-7 utilizes CD46 and DSG2 as functional co-receptors that act synergistically to mediate efficient infection." (PMID 41989164, 2026). "We noted that staining of DSG2, CD46, and CAR dropped to about 50%, yet there was an increased infection of HAdV-B3, -B11, and -C5, ranging between ca 50% and up to 400%." (PMID 40980888, 2025). "Virus strains that showed a dependency on CD46bov when comparing infection of MDBK WT and MDBKΔCD46 cells were further studied by infecting MDBKΔCD46 cells rescued with CD46-CTL or CD46-CTS." (PMID 34839792, 2022). "Because CD46 also serves as a receptor for other viruses (HHV-6, BVDV pestivirus, and adenoviruses B/D), this axis is likely to activate autophagy upon infection by additional pathogens." (PMID 37425656, 2022).
infection (continued). "While most HAdVs initiate infection by high affinity/avidity binding of their fiber knob (FK) protein to either coxsackievirus AdV receptor (CAR), CD46 or desmoglein (DSG)-2, MAdV-1 (M1) infection requires arginine-glycine-aspartate (RGD) binding integrins." (PMID 34910784, 2021). "Several studies revealed that the respiratory epithelium expresses CD46 and CAR and infection by respiratory Ads including Ad5 is well studied in respiratory cells." (PMID 34208817, 2021). "This activation is a direct consequence of its interaction with CD46 and translates into both LC3-II formation and LC3-positive puncta formation with a maximum reached 1.5 h after infection." (PMID 32274388, 2020). "Whereas binding of Ad3 fiber knobs to DSG2 can open tight junctions and expose CD46 for interaction with Ad3,38 these data suggest that DSG2 plays a more predominant role than CD46 in ONCOS‐102 viral attachment and infection of EOC cells." (PMID 31944306, 2020). "This blinding reduces the potential infection of CD150- and CD46-positive normal cells because CD150 is expressed on the surface of normal hematopoietic stem and progenitor cells, while high CD46 expression characterizes glandular cells of many organs." (PMID 33291506, 2020). "Nevertheless, our results indicate that CD46-cyt1 and GOPC play an important role in the autophagy response to Ngo-infection." (PMID 30753248, 2019). "Autophagy is induced through the CD46-cyt1/GOPC pathway and this response kills Ngo invading cells early in infection." (PMID 30753248, 2019). "Also, the role of CD46 in viral entry of epithelial cells and trophoblasts may be dependent on intracellular signaling molecules following virus interaction with cell-type specific CD46 protein-containing complexes that mediate downstream infection steps." (PMID 31221976, 2019). "Autophagy is induced through the CD46-cyt1/GOPC pathway, intracellular Ngo are located in autophagosomes, and Ngo invading cells early in infection are killed." (PMID 30753248, 2019). "We knocked down CD46-cyt1 in ME180 cells using CD46-cyt1 siRNA (Cyt-1), and examined LC3-II levels upon Ngo infection." (PMID 30753248, 2019). "We used flow cytometry analysis to quantify the cell-surface levels of CD55, CD46, and CD59 during infection." (PMID 30190327, 2018). "Other viruses, like measles virus (CD46), HIV (CD4), and EBV (CD21), also follow similar strategies of receptor downregulation after infection." (PMID 29093709, 2017). "These delays were similar to the shifts observed between infection at MOI = 1 and 0.1, suggesting that the anti-CD46 mAb inhibited approximately 90% of the infection." (PMID 26539644, 2015). "In contrast, infection of the cell line with the 65 kDA CD46 isoform resulted in an initial increase of surface GP96, which started to decrease 1day post infection." (PMID 25470779, 2014). "Notably if MV was selected on cells expressing SLAM as the sole receptor instead of CD46, selection pressure may have selected for escape mutations that did not compromise infection via SLAM." (PMID 23300970, 2013). "The top pathway for RA, the KEGG “Measles” pathway, contains genes involved in immune response cascades triggered by infection of measles virus, including the cellular receptors expressed for measles virus such as SLAM and CD46." (PMID 24098138, 2013). "Consistent with earlier work, regulators of complement activation, CD46, CD55 and CD59, were slightly enhanced after VV and VV:ΔHA infection (unpublished results)." (PMID 21901096, 2011). "Cell lines expressing TLR9, permissive to infection by both adenoviral serotypes utilizing the Coxsackievirus-AdV Receptor (CAR) and serotypes utilizing CD46, show a preferential induction of TLR9-mediated events by AdVs utilizing CD46 for their entry." (PMID 19088911, 2008).
infection (continued). "At 24 h post-infection, high numbers of bacteria (7×104 CFU/ml) were collected from nasal washes of CD46 transgenic mice, with over 95% of the recovered bacteria being bioluminescent meningococci." (PMID 17311106, 2007). "Previous studies have identified CD46 and desmoglein-2 (DSG2) as potential receptors for certain group B adenoviruses; however, the receptor usage of HAdV-7 infection remains unclear." (PMID 41989164, 2026). "In pseudotyped systems using species C HAdV backbones, whose hexons bind weakly or not at all to CD46, fiber knob:sialic acid interactions become more critical, and neuraminidase treatment reduces infection of such constructs." (PMID 40980888, 2025). "In this study, we demonstrate that HAdV-D types preferentially use CD46 for entry and infection, rather than CAR, DSG2, or sialic acid-containing glycans." (PMID 40980888, 2025). "Compared to WT and EV cells, deletion of CD46 strongly reduced the number of hexon‐positive cells upon infection with GoraVir but not HAdV‐C5, in both MiaPaCa2 and A549 cells." (PMID 38037840, 2024). "As expected, the MIA PaCa‐2 CD46‐KO cell line showed no killing upon infection with GoraVir at any of the MOI tested." (PMID 38037840, 2024). "As highlighted earlier, TKO/CD55 and TKO/CD55/CD46/TM pigs raised under the same conditions showed no signs of infection, suggesting that general housing environments are generally safe." (PMID 39902050, 2024). "Analysis of YPet expression revealed a significant reduction in ICVB-1042 infection in the absence of CD46 protein (48% YPet+ in CD46+ cells versus 2.0% YPet+ in CD46- cells), whereas Ad5-YPet infected both cell types with similar efficiencies as expected." (PMID 39271928, 2024). "The role of CD46bov as a receptor for BVDV-1 and -2 was demonstrated by blocking infections using anti-CD46bov mabs or a polyclonal rabbit anti-CD46bov serum and by CD46-transfection of non-permissive porcine cells." (PMID 34839792, 2022). "This agrees with both our SPR and modeling data and suggests that, although weak binding of CD46 was observed, CD46 engagement was not robust enough to result in productive infection." (PMID 35399606, 2022). "There was no significant increase in infection of CHO cells expressing CD46 compared with CHO-K1 cells with both HAdV-C5 and HAdV-D10." (PMID 35399606, 2022). "For BVDV, bovine complement regulatory protein 46 (CD46bov) has been identified as a receptor by blocking infections using anti-CD46bov mAbs or serum, and by CD46-transfection of non-permissive porcine cells." (PMID 36298858, 2022). "To investigate the receptor usage, we determined the transduction capacity of HAdV-20-42-42-Luc in various cell lines, expressing or lacking CAR, sialic acid-containing glycans, DSG2, or CD46 isoforms, by measuring the luciferase levels after infection." (PMID 34469243, 2021). "It seems to be important only for virus uptake from the supernatant, whilst cell-to-cell transmission and infection of polarized alveolar epithelial cells from the basal membrane are independent of CD46." (PMID 34959575, 2021). "Although a slight increase in the CD46-high population was observed at the 24 h time point, the expression corresponding to pre-infection levels was not attained." (PMID 33652918, 2021). "In a CD46 blocking experiment, the addition of an antibody directed against CD46 almost completely inhibited apical infection, whereas basolateral infection was not affected." (PMID 33300445, 2021). "The observation that the CD55 mRNA levels declined at later times post-infection whereas the protein levels did not suggests that differences in turnover rate contribute to the greater expression of CD55 compared to CD46." (PMID 33652918, 2021).